LATS1 (large tumor suppressor kinase 1)
Diseases named in the same sentence as LATS1 in open-access papers (continued):
Sharing a sentence is not in itself a finding about the gene and the disease.
cancer (172 papers, 2008 to 2025). A tumor composed of atypical neoplastic, often pleomorphic cells that invade other tissues. "Although dysregulation of LATS1 has been linked to cancer development and progression, its clinical value as a validated biomarker remains under investigation." (PMID 40699764, 2025). "Dysregulation of the Hippo pathway is implicated in many types of cancers with downregulated LATS1/2 signaling, resulting in increased accumulation of active YAP1 in the nucleus 33-36." (PMID 39781521, 2025). "Phase 1 clinical trials are currently assessing different YAP/TAZ-TEAD inhibitors in patients with mesothelioma and other cancers harboring NF2/LATS1/LATS2-mutations and tumors with functional YAP/TAZ fusions or otherwise elevated YAP/TAZ levels." (PMID 38538573, 2024). "Genetic alterations in LATS1/2, including mutations, deletions, and promoter hypermethylation, have been identified in several types of human cancer." (PMID 38383447, 2024). "In some types of cancer there is evidence of mutations in LATS1, and of LATS1 inactivation through promoter hypermethylation in others." (PMID 37151295, 2023). "The acquired expression of K14 in these luminal-derived carcinomas indicated that loss of LATS1/2 confers markers of luminal-basal fate plasticity to the expanding cell population." (PMID 36443313, 2022). "GSEA with our LATS-null ranklist displayed a strong enrichment for upregulated genes in the Brca1f/f; p53f/+; Blg-Cre model, suggesting a correlation between LATS1/2 inactivation and basal-like carcinomas driven by the Brca1 mutation." (PMID 36443313, 2022). "In confluent cultures, loss of Ser127 phosphorylation and LATS1/2 activity with persistent nuclear localization of YAP is a hallmark of cancer cells." (PMID 32231000, 2020). "Though the precise mechanism remains to be elucidated, it is likely that nucleic-acid-rich extracellular vesicles (EVs), released from LATS1/2-deficient cancer cells, stimulate the host nucleic-acid-sensing TLR signaling to induce a type I interferon response." (PMID 31052239, 2019). "Reduced LATS1 kinase activity is associated with enhanced cell proliferation, and LATS1 activity is often constitutively reduced in cancer cells." (PMID 29088716, 2017). "Malfunction of these critical signaling modules such as YAP/TAZ, MAT1/2 and LATS1/2 due to deregulated PTMs has been linked to a variety of human diseases such as cancer." (PMID 27042197, 2016). "In the Catalogue of Somatic Mutation in Cancer (COSMIC) database, approximately 1% to 2% of the more than 5,000 unique human cancer samples contain nonsynonymous mutations in Lats1 or Lats2." (PMID 25097728, 2014). "Recently, these Lats1/2 cancer mutations were shown to disrupt a number of Lats1/2 functions, including kinase activity, suppression of YAP activity, and tissue growth properties." (PMID 25097728, 2014). "In summary, while loss-of-function of Lats1 can predispose to cancer, there is compelling evidence both from transgenic mouse models and from human cancers that Lats1 can be overexpressed in tumors." (PMID 19656388, 2009). "We conclude that, similarly to other genes involved in mitotic checkpoint, cancer can be associated with either loss-of-function or overexpression of Lats1." (PMID 19656388, 2009). "Genetic studies demonstrated that the loss of LATS1 in mouse, and of its ortholog wts (warts) in Drosophila, is associated with increased cancer incidence." (PMID 19656388, 2009). "Loss-of-function of warts in Drosophila and of Lats1 in the mouse has been shown to increase the susceptibility to cancers in various tissues." (PMID 19656388, 2009). "Loss of Lats1 and its ortholog warts has been associated with increased susceptibility to various types of cancers." (PMID 19656388, 2009). "This protective function of Lats1 against cancer has been linked to its role in cell cycle progression during mitosis." (PMID 19656388, 2009).
cancer (continued). "In addition, various mutations in LATS1/2 were found in human cancers, including uterine endometrial carcinoma." (PMID 35409214, 2022). "However, in our study, we observed the role of the LATS1/2 mutation in modulating cancer immunity is the most prominent in human MPM compared with other cancer types, suggesting tissue-specific immunoregulation." (PMID 33805359, 2021). "Likewise, a LATS1/2 have been associated with cancer cell growth, suppression of cancer immunity and breast cancer progression." (PMID 31083564, 2019). "While LATS1/2 deficiency showed a significant increase in anchorage-independent cancer cell growth in vitro, their growth in vivo in immune-competent mice is severely compromised due to the induction of strong anti-cancer immune responses." (PMID 31052239, 2019). "Decreased level of LATS1 immunoreactivity in ccRCC cells, as observed in the present study, corresponds to the analysis of LATS1 gene expression on another set of ccRCC patients where we observed strong association between decreased LATS1 mRNA and protein contents in cancer tissue lysates." (PMID 29850494, 2018). "From human cancer genome projects, an increasing number of mutations in LATS1/2 are detected." (PMID 25482410, 2015). "Thus, in human malignant tumors, deficiency in Lats1 and/or Lats2 might promote overexpression of Cdc25B, leading to centrosome overduplication and, ultimately, to cancer progression." (PMID 26530630, 2015). "However, LATS1 mutations and biological significance in cancers remain unidentified." (PMID 25628642, 2014). "ITCH, the first identified negative regulator of LATS1, promotes cancer cell proliferation by mediating the degradation of LATS1 and enhancing the nuclear translocation of YAP." (PMID 40535763, 2025). "In cancers, however, dysregulation of Hippo signaling, often through the loss of kinases MST1/2 and LATS1/2, activates YAP/TAZ coactivators." (PMID 41155227, 2025). "In cancers with low LATS1 expression, CRISPR activation of LATS1 restored Hippo pathway function and suppressed YAP/TAZ oncogenic activity, thereby inhibiting tumorigenesis." (PMID 40895190, 2025). "The re‐expression of LATS1/2 and other upstream Hippo pathway components using viral vectors has been investigated in cancer models." (PMID 40895190, 2025). "To eliminate the possibility that an increase in p21 protein expression occurred due to cell growth arrest and senescence, we examined the accumulation of other REGγ targets, including Lats1, IκBε, and p16, in various cancer cell lines." (PMID 40091835, 2025). "Although the Hippo pathway has been implicated in human cancers, mutations or deletions of the pathway components, such as the MST1/2 or LATS1/2 kinases, are rarely detected in cancers." (PMID 38746415, 2025). "This study highlighted that LATS1/2 plays a crucial role in cancer stem cell renewal by regulating the Hippo pathway, EMT, and cell division." (PMID 40699764, 2025). "When analyzing enrichment of a previously curated list of conserved YAP/TAZ target genes in cancer across all clusters in our single cell data, we observed the strongest enrichment in the clusters containing LATS1/2-KO epithelial cells, myCAFs, and iCAFs." (PMID 39953252, 2025). "We observed a striking presence of myCAFs immediately adjacent to the mammary ducts and developing carcinomas in Lats1/2-KO mice, whereas iCAFs and PVLs were dispersed throughout the stroma farther from ducts." (PMID 39953252, 2025). "Histology analysis indicated increased expression of Integrin β1 in Lats1/2-KO carcinomas, with increased expression in both the epithelia and stroma of LATS1/2-KO mice relative to controls." (PMID 39953252, 2025). "Consistent with the growth inhibitory effect of LATS1/2, the deletion of LATS1/2 promoted cancer cell growth in vitro." (PMID 38566194, 2024). "It was shown that, independently of its kinase activity, LATS1/2 can inhibit human cancer cell proliferation and induce a G2/M arrest." (PMID 38803357, 2024).
cancer (continued). "The following animal experiments also indicated that overexpressing SNHG17 obviously impaired the anti-cancer effect of co-treatment of palbociclib and fulvestrant accompanied by decreased LATS1 and increased ER-α levels." (PMID 37924380, 2024). "Although initial investigations suggested that depletion of LATS1/2 (thus activating YAP/TAZ) enhances cancer immunity, a growing body of evidence now supports that, on the whole, YAP/TAZ function as suppressors of antitumor immunity." (PMID 38067201, 2023). "CCG-1423 has been shown to inhibit the transcriptional signaling by RhoA GTPase family and inhibit proteins and genes, such as β-catenin, TAZ, and p-LATS1, which are involved in promoting proliferation of cancer cell lines." (PMID 36232837, 2022). "The LATS1 effect, however, depends on a mechanically competent cytoskeleton, and its expression can be very variable in different cancer cells." (PMID 35455997, 2022). "In contrast, LATS1/2 knockout across multiple types of cancer cells in xenograft studies stimulates the anti-cancer immune response via release of nucleic acid-rich extracellular vesicles." (PMID 35119068, 2022). "Deletion of LATS1 turns non-invasive cancer cells grown at high densities (trans-endothelial invasion), similar to those grown at low densities." (PMID 35409214, 2022). "Loss of expression of RASSF1A in A375 is due to DNA methylation of the gene promotor, and the expression of MST1/2 and LATS1/2 in cancer also can be regulated by DNA methylation." (PMID 36038253, 2022). "Here the authors show that conditional deletion of LATS1/2 in the mature mouse luminal mammary epithelium leads to luminal-basal plasticity and development of basal-like carcinomas." (PMID 36443313, 2022). "Interestingly, we observed that Sox9+/ER− cells expand following LATS1/2 deletion, suggesting that loss of LATS1/2 drives the proliferation of Sox9+/ER− luminal progenitor-like cells and that these carcinomas may originate from a Sox9-expressing luminal population." (PMID 36443313, 2022). "Our analysis of carcinomas that develop upon luminal LATS1/2 deletion showed widespread expression of Sox9, particularly in expanding K8+K14+ cells." (PMID 36443313, 2022). "Further, EGFR-targeting therapies suppress YAP/TAZ, and loss of LATS1/2-mediated YAP/TAZ activation confers therapy resistance, thus offering insights into potential drug resistance mechanisms in cancers with activated EGFR." (PMID 34725466, 2021). "In other cancers, deletion of LATS and the resultant up-regulation in YAP/TAZ activity resulted in uncontrolled expansion of Sox2-positive cells, whilst LATS1/2 activity can trigger self-renewal of cancer stem cells in aggressive oral cancer." (PMID 33557087, 2021). "Of note, the CD8+ T-cell-related immune signature is mostly dysregulated in MPM with the LATS1/2 mutation that leads to Hippo-YAP activation, compared with other cancer types." (PMID 33805359, 2021). "Further delineation of WBP2 and its implications in LATS1/2 kinase activity will provide more insights into the development of anti-WBP2 therapeutics for Hippo-dysregulated cancers." (PMID 34831354, 2021). "Previous evidence indicated that Nitidine chloride treatment significantly enhanced the level of p-LATS1 in cancer cells." (PMID 34716294, 2021). "MGO-induced post-translational glycation of Hsp90 affects its activity with a consequent decrease in large tumor suppressor 1 (LATS1) expression, thereby promoting cancer cell growth and proliferation." (PMID 34947850, 2021). "This highlights the dual functions of LATS1/2 in cancer and reflects the crucial role of Hippo kinases in regulating tissue homeostasis." (PMID 34150758, 2021). "Hippo/YAP signaling pathway has been recognized as a linchpin in cancer therapy; dysregulation of core components (MST1/2, LATS1/2, YAP, etc.)associates with initiation, migration, invasion as well as therapeutic resistance of various types of cancer." (PMID 33292299, 2020).
cancer (continued). "For the data set of OV, 67 genes were identified by univariate Cox regression to be significantly associated with the cancer and seven of them, namely COL1A1, COL3A1, RPL10, ARHGAP5, LATS1, TSHR and SLC34A2, were found in the CGC data set." (PMID 32429941, 2020). "In several cancer types, the increase of LATS1 and 2 has been reported, and the expression levels are correlated with invasive and migratory capacities." (PMID 33304925, 2020). "Silencing LATS1&2 increased the abilities of CAFs to remodel gels and promote cancer cell growth, in line with their negative role in YAP function." (PMID 30631061, 2019). "Nevertheless, the biological roles of LATS1/2, as well as the mechanisms by which they enable cancer cells to acquire and maintain CSC properties, are incompletely understood." (PMID 30800215, 2019). "A recent study discovered that Lats1/2 knockout cancer cells secreted DNA containing exosomes to promote T help cell type 1 response and created an antitumor inflammatory environment." (PMID 31513574, 2019). "In contrast, LATS1 depletion augmented cancer cell plasticity, skewing luminal B tumors towards increased expression of basal-like features, in association with increased resistance to hormone therapy." (PMID 30456386, 2018). "LATS1/2 double knockout (DKO) (or YAP/TAZ-overexpressing) mouse cancer cells were shown to be highly tumorigenic in vitro, while proving to be poorly tumorigenic in vivo in immunocompetent mice, compared to their wildtype parental controls." (PMID 29597279, 2018). "Our results support a model that LATS1 is responsible for TNFAIP8 induced change of cancer cell growth and Hippo signaling, which is further supported by the fact of TNFAIP8/LATS1 interaction." (PMID 28152516, 2017). "This distribution is distinct from that of the human LATS1 protein, which localizes at interphase centrosomes in human cancer cells." (PMID 26530630, 2015). "The aim of the present study was to measure the expression of LATS1 in Yap-downregulated cancer cells." (PMID 25625370, 2015). "The Large Tumor Suppressor 1 (LATS1) is a serine/threonine kinase and tumor suppressor found down-regulated in various human cancers." (PMID 23573293, 2013). "While inactivation of Lats1/wts in mouse and Drosophila can increase cancer incidence, results from the present study demonstrate that Lats1 is a transcriptional target of CUX1 that can be overexpressed in tumors of various tissue-types." (PMID 19656388, 2009). "Due to the conserved role of LATS1 in suppressing tumorigenesis, we speculate that distinct LATS1 O-GlcNAc sites will be identified in different types of cancer in the future." (PMID 41338457, 2025). "As the carcinomas that form in this model are driven by epithelial-specific inactivation of Lats1/2, we hypothesized that the epithelium must signal to other cell populations to elicit the observed stromal changes." (PMID 39953252, 2025). "We next sought to define the major functions of iCAFs, myCAFs, and PVLs in Lats1/2-null carcinomas." (PMID 39953252, 2025). "We next sought to validate changes in ECM proteins histologically in Lats1/2-null carcinomas." (PMID 39953252, 2025). "To define signals that originate from macrophages in Lats1/2-null carcinomas, we performed CellChat analysis designating macrophages as sender cells, which predicted several pathways as axes between macrophages and other cell types, with the strongest signals going to EYFP+ lineage-traced cells." (PMID 39953252, 2025).
cancer (continued). "A cancer with a high frequency of mutational YAP/TAZ-TEAD activation is malignant pleural mesothelioma, an asbestos-induced lung tumor where forty percent of patients have deletions or loss-of-function mutations in LATS1, NF2, RASSF1, or SAV170." (PMID 38538573, 2024). "Given that the coimmunoprecipitation data showed that WWP2 was an interacting partner of LATS1, we speculated that the cancer-promoting functions of WWP2 might be related to the Hippo-YAP1 pathway." (PMID 36803368, 2023). "In general, LATS1 plays a critical role in orchestrating the Hippo-YAP1 pathway, thereby subsequently leading to the inhibition of proliferation and invasion in cancer cells, indicating that targeting LATS1 could be a promising strategy for GC treatment." (PMID 36803368, 2023). "To further investigate the impact of LATS1 on cell identity, we, therefore, utilized these cell surface markers, which strongly segregated between the luminal/luminal progenitor (henceforth called “luminal”) and basal-like subpopulations of both WT and Lats1-CKO PyMT cancer cells." (PMID 36443319, 2022). "Indeed, YAP and/or TAZ have the ability to interact with SNAIL, SLUG, and/or ZEB1 during development or cancer progression, whereas LATS1/2 also regulate chromosomal instability." (PMID 35859006, 2022). "Furthermore, we previously showed that LATS1/2 are required for spheroid formation of cancer stem-like cells." (PMID 35859006, 2022). "This difference may relate to the potential intersection of LATS1/2 deletion with other oncogenic signals existing in those cancer cell lines, which may render them unable to attain a basal-like state." (PMID 36443313, 2022). "Therefore, single genetic events impacting STK3/4 and LATS1/2 will be insufficient to drive cancer formation." (PMID 34150758, 2021). "Finally, LATS1/LATS2 knockdown can rescue the cancer cell killing effect from the combination treatment of AMG510 and IN10018, suggesting Hippo kinase signaling is involved in this FAK‐YAP related drug response." (PMID 34151545, 2021). "And LATS1/2 has been reported have a suppress role in cancer immunity, and this phenomenon may be a reason why YAP1 cytoplasmic localization is associate with the progression and poor prognosis of CRC." (PMID 33240680, 2020). "Importantly, in a variety of cancers, high expression levels of CDC25B were related with loss of function of LATS1/2 or mutation in N-terminal region of LATS1/2." (PMID 32867200, 2020). "Moreover, the cell type-dependent functions of LATS1/2 in promoting or suppressing cancer cell growth became apparent." (PMID 31052239, 2019). "Canonical signaling through the Hippo pathway core components (MST1/2, LATS1/2, YAP and TAZ) is important for development and tissue homeostasis while aberrant signaling through the Hippo pathway has been implicated in multiple pathologies, including cancer." (PMID 29597279, 2018). "Overall, the expression pattern changes in the mouse Lats1-CKO PyMT tumors agreed well with those seen in human luminal cancer cell lines (MCF7 and ZR75-1) subjected to either up- or down-modulation of LATS1, supporting the human relevance of the Lats1-CKO PyMT model." (PMID 30456386, 2018). "The identification of inactivating mutations in two key components of the Hippo–YAP pathway, LATS1 and PTPN14 genes, provides clear evidence of the involvement of this signaling cascade in BCC, adding BCC to the broad group of human cancers with a deregulated Hippo–YAP axis." (PMID 29165358, 2017). "Few studies indicate the relationship between 17-AAG and LATS1 in cancers." (PMID 25712415, 2015). "Therefore, LATS1 mutants (R657C, R694C and R697G) and LATS2 mutants (R623W and R645L), are expected to become inactive in human cancer due to loss of interactions with LATS activators such as MOB." (PMID 25482410, 2015). "Therefore, it is possible WWP1 and Itch regulates LATS1 stability in different cancer types and physiological conditions." (PMID 23573293, 2013).